BDH2 (3-hydroxybutyrate dehydrogenase 2)
Description:
NAD(H)-dependent dehydrogenase/reductase with a preference for cyclic substrates (By similarity). Catalyzes stereoselective conversion of 4-oxo-L-proline to cis-4-hydroxy-L-proline, likely a detoxification mechanism for ketoprolines. Mediates the formation of 2,5-dihydroxybenzoate (2,5-DHBA), a siderophore that chelates free cytoplasmic iron and associates with LCN2, thereby regulating iron transport and homeostasis while protecting cells against free radical-induced oxidative stress. The iron-siderophore complex is imported into mitochondria, providing an iron source for mitochondrial metabolic processes in particular heme synthesis (By similarity). May act as a 3-hydroxybutyrate dehydrogenase.
Synonyms: DHRS6; SDR15C1; UCPA-OR; FLJ13261; UNQ6308; PRO20933; EFA6R
Tractability: Small molecule: a structure with a bound ligand is known; it has a high-quality binding pocket. PROTAC: ubiquitination databases record sites on it; its protein half-life has been measured.
Target class: Enzyme; Oxidoreductase
Gene: Protein-coding gene on chromosome 4 (103,077,592 to 103,099,880, reverse strand). Ensembl gene ENSG00000164039.
Subcellular location: Cytoplasm
Subcellular location (Human Protein Atlas): Cytosol
Pathways (Reactome):
Metabolism: Synthesis of Ketone Bodies
Gene Ontology:
Molecular function: 3-hydroxybutyrate dehydrogenase activity; 4-oxoproline reductase activity; NAD binding; protein binding; oxidoreductase activity, acting on the CH-CH group of donors, NAD or NADP as acceptor
Biological process: epithelial cell differentiation; fatty acid beta-oxidation; heme metabolic process; siderophore biosynthetic process
Cellular component: cytoplasm; cytosol; extracellular exosome; mitochondrion
Genetic constraint (gnomAD): Loss-of-function variants: 21 observed, 24.13 expected, observed/expected ratio (o/e) 0.87, 90% interval 0.62 to 1.25. The upper end of that interval is the gene's LOEUF score, 1.25, which puts it in group 5 of 6, group 1 being the genes least tolerant of losing a copy. Missense variants: 211 observed, 247.88 expected, observed/expected ratio (o/e) 0.85, 90% interval 0.76 to 0.95. Synonymous variants: 67 observed, 88.25 expected, observed/expected ratio (o/e) 0.76, 90% interval 0.62 to 0.93.
Homologues: Orthologues: chimpanzee BDH2 (100% identical), macaque BDH2 (99% identical), pig BDH2 (94% identical), rabbit BDH2 (94% identical), dog BDH2 (92% identical), mouse Bdh2 (91% identical), guinea pig BDH2 (89% identical), rat Bdh2 (77% identical), zebrafish bdh2 (76% identical).